GABBR1 (gamma-aminobutyric acid type B receptor subunit 1)
Diseases named in the same sentence as GABBR1 in open-access papers (continued):
Sharing a sentence is not in itself a finding about the gene and the disease.
autism (6 papers, 2017 to 2025). Persistent deficits in social interaction and communication and interaction as well as a markedly restricted repertoire of activity and interest as well as repetitive patterns of behavior. "Because of the measured difference in GABAB1 protein expression in autism, examining a potential link between the autism-associated GABBR1 variant and these expression differences should be a priority." (PMID 33958984, 2021). "Because of the relative likelihood that autism-associated intron variants such as those found in GABBR1 and KCNN2 would result in transcriptomic changes, transcriptomics should be a primary focus of future research on these genetic variants’ impact." (PMID 33958984, 2021). "Similar to the autism-associated epigenetic regulation of GABBR1 observed in the literature, an autism-specific epigenetic regulation of SK2 ion transport activity was noted." (PMID 33958984, 2021). "The GABBR1 variant associated with autism—variant rs740883—is an intronic variant in which a thymine replaces an adenine." (PMID 33958984, 2021). "The autism-associated GABBR1 and KCNN2 genetic variants have been highlighted as such only recently, and therefore there is an opportunity to collect more definitive experimental data, which can inform the modeling of sensory processing dynamics as they relate to these variants." (PMID 33958984, 2021). "The Alternative Splice Site Predictor (ASSP) tool (Wang and Marín, 2006) determined short windows containing the loci for each of the GABBR1 and KCNN2 autism-associated genes." (PMID 33958984, 2021). "In Drugbank, two potential therapeutic drugs, Acamprosate (GABBR1 inhibitor) and Bryostatin 1 (CASP8 inhibitor), were inferred as potential influencers of autism." (PMID 39038939, 2024).
bipolar disorder (5 papers, 2017 to 2024). A disorder of the brain that causes unusual shifts in mood, energy, activity levels and the ability to carry out day-to-day tasks. "Reductions in GABBR1 and GABBR2 proteins are observed in prefrontal cortex of subjects with bipolar disorder." (PMID 33006978, 2020). "Additionally, a post-mortem study revealed reduced protein expressions of GABBR1 and GABBR2 in the cerebellum of patients with bipolar disorder." (PMID 39228919, 2024).
glioma (4 papers, 2009 to 2024). A benign or malignant brain and spinal cord tumor that arises from glial cells (astrocytes, oligodendrocytes, ependymal cells). "Western blot also showed that the protein levels of CALCRL, SERPINE1, and MMP14 in glioma cells were basically higher than human glioma cells, whereas GABBR1 has the opposite trend, which is consistent with the results qRT-PCR and IHC." (PMID 37488455, 2023). "The most notable lncRNA is LINC00599, which has DBSs in many NGS genes in most gliomas, including GABBR1, NRCAM, PTPRS, GLRB, GRIA4, GRIK3, and MAP2, and the most notable NGS gene is MAP2, which is associated with microtube assembly and regulated by multiple lncRNAs through the same DBS." (PMID 37693314, 2023). "The western blot results also confirmed the differences of CALCRL, GABBR1, SERPINE1, and MMP14 in normal human astrocyte cell and glioma cells." (PMID 37488455, 2023). "Except for GABBR1 and SEMA4D, other genes are upregulated in glioma tissues." (PMID 37488455, 2023).
lung carcinoma (4 papers, 2017 to 2026). "It is demonstrated that GABBR1 overexpression in lung cancer cells suppresses tumor growth both in vitro and in vivo." (PMID 42157924, 2026). "Overall, these findings identify valerate as a novel immunomodulatory metabolite and propose targeting GABBR1 as a promising strategy to potentiate cancer immunotherapy in lung cancer." (PMID 42157924, 2026). "Six genes showed particularly stronger expression pattern in lung cancer tissues, as compared to normal lungs, which demonstrated that these six genes (GABBR1, PDE4B, PDE4C, ADCY6, ADCY1 and GIPR) had more likelihood of being direct targets of miR-542-5p in lung cancers." (PMID 28927388, 2017).
alcohol dependence (3 papers, 2018 to 2024). Physical and psychological dependence on alcohol. "Among the significant associations detected by both SNP-based and haplotype-based methods, the GABBR1 gene showed significant biological implications, and was stably expressed in case of alcohol dependence." (PMID 38448893, 2024).
Hypertension (3 papers, 2016 to 2024). The presence of chronic increased pressure in the systemic arterial system. "The functional role of the elevated transcription of Gabbr1 in adrenal glands is not known and has to be studied, as it might be essential for stress-sensitive hypertension development in ISIAH rats." (PMID 28105924, 2016).
Intellectual disability (3 papers, 2021 to 2026). "Here, we investigated the functional impact of seven de novo missense variants in GABBR1 and GABBR2 identified in individuals with autism spectrum disorder, intellectual disability, and/or attention deficit/hyperactivity disorder." (PMID 41803176, 2026).
prostate carcinoma (3 papers, 2018 to 2025). A carcinoma that arises from epithelial cells of the prostate gland. "Beyond its neurological roles, GABBR1 plays a critical oncogenic role in colorectal and prostate cancer." (PMID 41301871, 2025). "For the first time, in this study we show the role of GABA and GABAB receptor 1 (GABBR1) expression in GRP secretion in NE-like prostate cancer cells." (PMID 29980692, 2018).
viral infection (3 papers, 2015 to 2023). "Next, we constructed a ceRNA-associated molecular network involved in diabetes and viral infections for GABBR1." (PMID 37969011, 2023). "Then, we dissected the involvement of GABBR1 in diabetes and viral infections using a ceRNA dataset." (PMID 37969011, 2023). "In this study, we evaluated GABBR1 as a shared target between diabetes and viral infection (focusing on COVID-19) for drug development on the basis of numerous brilliant databases and bioinformatics tools (for details, seeSupplementary Methods)." (PMID 37969011, 2023). "In summary, we evaluated GABBR1 as a shared target between diabetes and viral infections for drug development." (PMID 37969011, 2023). "On the basis of these results, we achieved a shared interRNA mechanism between diabetes and viral infections, which consisted of GABBR1, HMGA1, and SMARCA4." (PMID 37969011, 2023). "From KEGG, we determined the relationships of GABBR1 with viral infections, such as “HTLV-I infection”." (PMID 37969011, 2023). "On the basis of these results, we determined the functional terms of interRNAs by GAD, KEGG, and HIV-related analysis, which further provided support for the involvement of GABBR1 in diabetes and viral infections." (PMID 37969011, 2023). "We extracted 100 interRNA genes of GABBR1 from the ENCORI repository to confirm the roles of GABBR1 in diabetes and viral infections." (PMID 37969011, 2023). "We then revealed signaling cells of GABBR1-centered network genes in diabetes and viral infections by profiling single-cell expression." (PMID 37969011, 2023). "We further analyzed interRNA-related signaling pathways involved in diabetes and viral infections for GABBR1." (PMID 37969011, 2023). "Therefore, we concluded that we obtained a shared ceRNA network between diabetes and viral infections, which consisted of GABBR1, PDGFRB, WNT2B, and hsa-miR-19b/a-3p." (PMID 37969011, 2023). "We also revealed the involvement of GABBR1 in diabetes and viral infections by an interRNA dataset." (PMID 37969011, 2023). "Because ceRNA can reflect direct molecular interactions, we extracted 500 ceRNA genes of GABBR1 from the ENCORI database to parse the functions of GABBR1 to confirm its potential roles in diabetes and viral infections." (PMID 37969011, 2023). "Using brilliant databases and bioinformatics tools, we identified GABBR1-centered ceRNAs formed by PDGFRB and WNT2B via hsa-miR-19-3p and RNA-RNA interactions with HMGA1 and SMARCA4 as shared molecules between diabetes and viral infection." (PMID 37969011, 2023).
Cerebral ischemia (2 papers, 2015 to 2024). Restriction of arterial blood supply to the brain associated with insufficient oxygenation to support the metabolic requirements of the tissue. "Selective continuous activation of GABBR1 can provide neuroprotection in vitro and in vivo models of cerebral ischemia." (PMID 38515838, 2024).
colon cancer (2 papers, 2021 to 2024). "However, irrespective of whether expression of GABAA or GABAB receptor subunits were altered in colon cancer, expression of particular receptor subtypes (GABRA1, GABRA5, GABRD, GABRE, GABRG1, GABRG3, GABBR1, and GABBR2) was significantly associated with poor clinical outcome." (PMID 38886975, 2024).
hepatocellular carcinoma (2 papers, 2018 to 2021). A malignant tumor that arises from hepatocytes. "GABBR1 is a different methylated gene in plasma cf-DNA in different early stage of hepatocellular carcinoma development." (PMID 29933410, 2018).
nasopharyngeal carcinoma (2 papers, 2018 to 2025). A carcinoma arising from the nasopharyngeal epithelium. "It is showed that multiple loci of GABBR1 within 6p21.3 are related to nasopharyngeal carcinoma." (PMID 29933410, 2018).
neuroblastoma (2 papers, 2025). Neuroblastoma (NB) is the most common solid, extracranial childhood tumor. "LINC00622 inhibits the activity of transcription factor AR and promotes GABBR1 expression to repress neuroblastoma cell growth." (PMID 40651979, 2025). "For example, linc00622 can increase the expression of GABBR1 in neuroblastoma (NB) cells, inhibiting NB proliferation, invasion, and migration." (PMID 40647484, 2025).
nicotine dependence (2 papers, 2009 to 2012). Physical and psychological dependence on nicotine. "These were two intronic SNPs in the gamma aminobutyric acid B receptor 1 (GABBR1) gene linked to nicotine dependence, predicted to influence alternative splicing." (PMID 23139751, 2012).
psychosis (2 papers, 2021 to 2025). "Among the 170 propsychotic target genes, 8 were a high-confidence psychosis risk gene (GRIN2A, DRD2, CYP2D6, CHRNB4, CHRM4, GABBR1, GRM3, CHRNA3)." (PMID 40701976, 2025).
temporal lobe epilepsy (2 papers, 2005 to 2022). A localization-related (focal) form of epilepsy characterized by recurrent seizures that arise from foci within the temporal lobe, most commonly from its mesial aspect. "Polymorphism G1465A in the GABBR1 gene has been suggested as a risk factor for non-lesional temporal lobe epilepsy (TLE); however, this genetic association study has not been independently replicated." (PMID 15799783, 2005).
asthma (1 paper, 2025). "One significant DMP (differentially methylated position) (α = 0.05/742,442) was detected in the NTR asthma EPIC dataset (cg26272069, GABBR1 gene), and 95 significant DMPs were detected in the NTR biobank 450k dataset (α = 0.05/411,169)." (PMID 40001554, 2025).
benign prostatic hyperplasia (1 paper, 2018). A non-cancerous nodular enlargement of the prostate gland. "We also measured levels of AR, ENO2, and GABBR1 in urine samples from patients with PCa (n = 10) and patients with Benign Prostatic Hyperplasia (BPH) (n = 5)." (PMID 29980692, 2018).
cerebral malaria (1 paper, 2025). A sequestration of Plasmodium falciparum in the brain, which can cause coma and/or seizures. "The Gabbr1 gene was found to be significantly over-expressed in the infected group that had been induced by cerebral malaria." (PMID 40260212, 2025).
chronic heart failure (1 paper, 2019). "The gamma-aminobutyric acid B-type receptor unit 2 (Gabbr1) expressed in paraventricular nucleus (PVN) is important in controlling sympathetic activity, and its upregulation attenuated sympathoexcitation in chronic heart failure." (PMID 30906419, 2019).
cocaine addicts (1 paper, 2013).
COVID-19 (1 paper, 2023). A disease caused by infection with severe acute respiratory syndrome coronavirus 2. "These clinical drug trials strongly confirm the valuable significance of GABBR1-centered network molecules in managing the coexisting diseases of diabetes and COVID-19." (PMID 37969011, 2023). "Finally, we refined drugs from chemicals targeting GABBR1-centered signaling molecules for treating diabetes and COVID-19." (PMID 37969011, 2023).
developmental and epileptic encephalopathy (1 paper, 2024). An epilepsy associated with developmental impairment that may be due to either the underlying etiology or the superimposed epileptic activity, or both. "Within the cohort of patients experiencing developmental and epileptic encephalopathy (DEE), WES has revealed genetic variants in novel genes (FGF12, GABBR1, GABBR2, ITPA, KAT6A, PTPN23, RHOBTB2, SATB2) and candidate epilepsy-associated genes (CAMTA1, FAT3, GABRA6, HUWE1, PTCHD1)." (PMID 39523358, 2024).
diabetes (1 paper, 2023). "GAD-related terms exhibited GABBR1 functional associations with diabetes." (PMID 37969011, 2023). "Nine terms of GAD revealed that GABBR1 can be involved in several diseases, including diabetes." (PMID 37969011, 2023).
drug dependence (1 paper, 2024). "The GABAergic system plays an important role in the mechanism of drug dependence and GABBR1 has been associated with MA dependence and relapse after rehabilitation." (PMID 38448893, 2024).
gastric cancer (1 paper, 2018). A primary or metastatic malignant neoplasm involving the stomach. "In addition, GABBR1 is associated with the survival time of patients with gastric cancer." (PMID 29933410, 2018).
language delays (1 paper, 2024). "Individuals with GABBR1 missense variants exhibit neurodevelopmental motor and language delays." (PMID 39038939, 2024).
lung adenocarcinoma (1 paper, 2024). A carcinoma that arises from the lung and is characterized by the presence of malignant glandular epithelial cells. "Among these, CSF3 and GABBR1 showed significantly reduced expression in lung adenocarcinoma tissues compared to normal tissues." (PMID 39727962, 2024).
lung squamous cell carcinoma (1 paper, 2024). "For lung squamous cell carcinoma, 11 genes were causally related, comprising COPA, NCSTN, U91328.19, GABBR1, IER3, HLA-DQB1-AS1, HLA-DQB2, ANKRD26, PKD2L1, PSMA4 and RAD51C." (PMID 38834983, 2024).
melanoma (1 paper, 2023). A malignant, usually aggressive tumor composed of atypical, neoplastic melanocytes. "In vitro study shows isoliquiritigenin interaction with gamma-aminobutyric acid type-B receptor subunit 1 and targeting of miR-301b/LRIG1 signaling pathways causes suppression of melanoma growth." (PMID 36985568, 2023).
renal cell carcinoma (1 paper, 2025). "Molecular docking findings indicate that the environmental endocrine-disrupting chemical BPA specifically interacts with key targets essential for the function of renal cell carcinoma cells, including CHRM3, GABBR1, CCR4, KCNN4, PRKCE, CYP2C9, HPGD, and FASN." (PMID 41301871, 2025).
Stroke (1 paper, 2022). Sudden impairment of blood flow to a part of the brain due to occlusion or rupture of an artery to the brain. "Stroke induced degradation of GABAB1 receptors could lead to the observed compensatory upregulation of GABBR1 transcript prevented by contralateral stimulation." (PMID 35723585, 2022).
tauopathy (1 paper, 2018). Neurodegenerative disorders involving deposition of abnormal tau protein isoforms (tau proteins) in neurons and glial cells in the brain. "To begin to address this question, we examined temporal expression of Gabbr1, Gabrb2, Gabrb3, and Gabrg2 in a mouse model of tauopathy that overexpresses human MAPT p.P301L37." (PMID 30546007, 2018).
type 2 diabetes (1 paper, 2013). "The GMDR has been successful in identifying the significant interaction of CHRNA4 with CHRNB2, NTRK2 with BDNF, and GABBR1 with GABBR2 in nicotine dependence, of LEPR and ADRB2 in obesity, and of HNF4A and KCNJ11 in type 2 diabetes (T2D)." (PMID 23626757, 2013).
vascular dementia (1 paper, 2025). A degenerative vascular disorder affecting the brain. "Both Mapk10 and Gabbr1 are considered potential targets for vascular dementia treatment." (PMID 40699779, 2025).
tumor (21 papers, 2008 to 2026). "100% and 69% of ACC tumor samples expressed transcripts encoding GABBR1 and GABBR2, with upregulation in 8% and 15% of patients, respectively." (PMID 33187258, 2020). "The Taiwan GWAS was the first study to associate GABBR1 with NPC and found elevated GABBR1 protein expression in NPC tumor tissues compared with the adjacent normal epithelial cells." (PMID 21283797, 2011). "The expression of GABBR1 gene in normal samples is higher than the tumor samples; however, the expression level of five miRNAs was opposite." (PMID 27230463, 2016). "Statistically, the GABBR1 gene showed a marginally significant association between the NPC tumor and non-tumor tissue specimens (P = 0.059)." (PMID 21283797, 2011). "However, in this same study expression of the GABBR1 protein in NPC tissues was also evaluated using immunohistochemical staining and the intensity of the GABBR1 signal in tumor cells was significantly higher than that detected in adjacent normal epithelial cells (P < 0.001)." (PMID 24367763, 2013). "This study identifies valerate as a biased ligand for GABAB receptor, which specifically binds the GABBR1 subunit, upregulates its expression, and thereby mediates CD8+ T cell anti-tumor immunity in NSCLC." (PMID 42157924, 2026). "Mechanically, in vitro and in vivo experiments validate that valerate-induced upregulation of GABBR1 stimulates the secretion of CXCL13, which in turn promotes robust infiltration and activation of CD8+ T cells within the tumor microenvironment." (PMID 42157924, 2026). "In contrast, the levels of ENO2, GABBR1, and MC1R were significantly elevated in tumor tissues compared with normal tissues." (PMID 35872794, 2022). "The most targeted tumour suppressors were phosphatase and tensin homolog (PTEN) and gamma-amino-butyric acid type B receptor 1 (GABBR1), inhibited by eight and five miRNAs, respectively." (PMID 34198662, 2021). "Common to both analyzed cohorts was the underexpression of GABBR1, and the overexpression of GABRD, in tumor vs normal tissues." (PMID 33187258, 2020). "Quantitative real-time polymerase chain reaction (qPCR) using 11 pairs of NPC biopsy samples confirmed the significant decline in GABBR1 and NEDD9 mRNA expression in the cancer tissues compared to the adjacent non-tumor tissue (p<0.05)." (PMID 21283797, 2011). "When comparing our gene expression analyses and genetic analyses, the cancer genes HLA-DPA1, HLA-DMB, DNAJA4, LY86, HCLS1, GABBR1, NUDT16 showed upregulation in tumor tissue compared to cell subpopulations and are located in chromosomal regions that showed losses in GSC and CD133pos./CD15pos. cells." (PMID 32634135, 2020). "In addition, we examined the mRNA expression levels of NEDD9 and GABBR1 in 10 matched-pairs NPC and adjacent non-tumor tissues by quantitative real-time PCR." (PMID 22880099, 2012). "Moreover, GABBR1 was down-regulated in all three NPC cell lines and in 8/11 tumor biopsy tissues compared with the non-tumor tissue." (PMID 21283797, 2011). "Furthermore, using the genotyping data and quantitative real-time PCR, they've identified several micro-deleted regions covering NEDD9 and GABBR1 genes and demonstrated that reduced expression of both genes in NPC tumor cells when compared to adjacent normal tissues." (PMID 22880099, 2012).